RNF31 (ring finger protein 31)
Diseases named in the same sentence as RNF31 in open-access papers (continued):
Sharing a sentence is not in itself a finding about the gene and the disease.
cancer (continued). "We thus hypothesized that sex may be a factor affecting RNF31 expression in cancer tissues." (PMID 37117215, 2023). "In this report, we first evaluated the expression of RNF31 across cancers in the TIMER database and found that RNF31 expression was significantly upregulated in multiple cancer cells compared with normal tissues." (PMID 37117215, 2023). "Previous studies have reported that RNF14, RNF31, RNF144B, RNF216 and ARIH1 mainly play carcinogenic roles, while ARIH2 and PARK2 generally play anticancer roles in malignant tumors." (PMID 35732617, 2022). "In order to compare the effects of RNF31 on LIHC and other cancers." (PMID 37117215, 2023). "To date, little is known regarding the role and mechanism of RNF31 in HCC, but understanding the role of RNF31 in HCC may be informative for both the diagnosis and treatment of this cancer." (PMID 35869046, 2022). "The pan-cancer analysis revealed RNF31 had no prognostic value in any of the 31 tumors." (PMID 36357839, 2022). "The functional role of RNF31 in human cancer is not thoroughly studied." (PMID 27460922, 2016). "In the TA of LLC‐bearing mice, a model of cancer cachexia but in C57BL/6 background, the mRNA levels of p47, Ufd2, Nploc4, and Herpud1 were all induced by about 50%, while Ufd1, Derl1, Rnf31, and Hsp90 did not change." (PMID 35611892, 2022). "Although RNF31 was firstly cloned from MCF-7 cells, it was not instantly studied in cancer area." (PMID 27460922, 2016).
infection (8 papers, 2020 to 2025). The state of being infected such as from the introduction of a foreign agent such as serum, vaccine, antigenic substance or organism. "Within the ubiquitin pathway, E3 ubiquitin ligases including HOIP (RNF31), TRAF2, and Pellino (PELI1) showed marked infection-dependent changes at the level of phosphorylation (e.g. RNF31_S445) and ubiquitination (e.g. PELI_K202 early, TRAF2_K313 late)." (PMID 34085925, 2021).
bacterial infection (3 papers, 2019 to 2022). "Of note, HOIP-mutated patients present with recurrent bacterial infections and hyper-inflammation, further supporting the potential therapeutic targets of RNF31 for suppressing TLR3-related inflammatory diseases." (PMID 36042206, 2022).
RNF31 also shares sentences with these, for which no sentence is quoted: dermatitis (6 papers); diffuse large B-cell lymphoma (5); myopathy (3); ovarian carcinoma (3); autoimmune disease (2); B cell lymphomas (2); cardiomyopathy (2); Cirrhosis (2); diabetes (2); Hepatitis (2); leukemia (2); liver cancer (2); metabolic dysfunction-associated steatotic liver disease (2); Obesity (2); acute myeloid leukemia (1); adenovirus infection (1); atopic dermatitis (1); Atrophy (1); autoinflammatory syndrome (1); cholangiocarcinoma (1); co-infection (1); colon adenocarcinoma (1); colorectal cancer (1); cortical dysplasia (1); COVID-19 (1); epidermodysplasia verruciformis (1); esophageal carcinoma (1); fibrosis (1); genetic diseases (1); glycogen storage disorders (1).
A further 49 diseases each share a sentence with RNF31 in 1 paper.